ENSG00000212391
Synonyms: LOC124900533
Gene: Small nucleolar RNA gene on chromosome 2 (226,968,989 to 226,969,122, reverse strand). Ensembl gene ENSG00000212391.
Gene Ontology:
Biological process: RNA processing
Cellular component: nucleolus
Homologues: Paralogues in human: SNORA48 (84% identical), SNORA48B (81% identical).